TNF (tumor necrosis factor)
Diseases named in the same sentence as TNF in open-access papers (continued):
Sharing a sentence is not in itself a finding about the gene and the disease.
metabolic syndrome (827 papers, 2005 to 2026). A cluster of metabolic risk factors for CARDIOVASCULAR DISEASES and TYPE 2 DIABETES MELLITUS. "These substances, including interleukin-6 (IL-6) and tumor necrosis factor-alpha (TNF-α), contribute to a state of chronic low-grade inflammation, a hallmark of metabolic syndrome and cardiovascular disease." (PMID 40217861, 2025). "This study focused on intermediate outcomes, including dyslipidemia and oxidative stress, and inflammation markers, such as TNF-α, IL-6, and CRP, which predict cardiovascular health risk." (PMID 39840146, 2025). "Adipose tissue, through cytokine secretion, sustains systemic inflammation—a hallmark of metabolic syndrome—further aggravated by neutrophil elastase activity and rhythmic macrophage secretion of Tumor Necrosis Factor Alpha (TNF-α) and interleukin-6 (IL-6)." (PMID 41303617, 2025). "Chronic inflammation is a hallmark of metabolic syndrome, and anthocyanins (320 mg/day for 4 weeks) can lower systemic inflammation by inhibiting proinflammatory factors like TNF-α and IL-6, thus alleviating metabolic syndrome symptoms." (PMID 40626227, 2025). "This study aimed to examine the associations between inflammatory markers (interleukin-6, tumor necrosis factor-alpha, high-sensitivity C-reactive protein) and metabolic syndrome, with markers of ovarian aging and cardiovascular risk." (PMID 40713717, 2025). "There were associations between dietary factors and some metabolic syndrome components and TNF-α DNA methylation levels." (PMID 38542788, 2024). "Obesity, a major component of metabolic syndrome, is associated with chronic inflammation and increased production of pro-inflammatory factors like TNF-α." (PMID 39310549, 2024). "Using in silico data analysis, we created an mRNA-miRNA panel (ZBP1, HSPA1B, MAPK3 & mir-5192) associated with pancreatic cell dysfunction and metabolic syndrome and involved in necroptosis-related TNF pathway." (PMID 38961451, 2024). "Our results suggest an association of higher TNF plasma concentrations with metabolic syndrome components, including dyslipidemia." (PMID 38396488, 2024). "Again, BJ was shown to alleviate hepatic steatosis in an animal model of diet-induced metabolic syndrome and cardiovascular risk via the reduction in IL-6 and TNF-α plasma levels and ROS generation." (PMID 38257152, 2024). "At a molecular level, BPA can cause dyslipidemia and oxidative stress, release proinflammatory cytokines and adipokines such as TNF-α and leptin, and activate certain transcription factors such as PPAR-y or binding protein 1c." (PMID 39519574, 2024). "In metabolic syndrome, the production of tumor necrosis factor α (TNF-α), a pathogenic contributor adipokine produced from enlarged adipocytes, induces chronic inflammation." (PMID 36768946, 2023). "In the presence of metabolic syndrome, however, enlarged white adipocytes produce TNF-α, which is an inflammatory pathogenic contributor adipokine." (PMID 36768946, 2023). "These conditions cause dysbiosis in gut microbiota, with increased Firmicutes and decreased Bacteroidetes populations, induce the production of the pathogenic contributor TNF-α, and decrease the protective adiponectin, leading to the onset metabolic syndrome." (PMID 36768946, 2023). "The association between inflammation and dyslipidemia has also been linked through TNF-α in a diabetic nephropathy urine model where the injection of TNF-α caused the accumulation of cholesterol and favored apoptosis." (PMID 36900438, 2023). "Disorders related to metabolic syndrome are induced by chronic inflammation through the production of the pathogenic contributor adipokine TNF-α." (PMID 37569540, 2023). "In patients with metabolic syndrome, increased serum levels of IL-6 and TNF-α have been found to be associated with the severity of metabolic syndrome development." (PMID 37796781, 2023).
metabolic syndrome (continued). "We have demonstrated that inflammatory cytokines such as TNF-α, IL-6, and IL-1β are soluble mediators linked with ventricular arrhythmias and contractile dysfunction in a rat model of metabolic syndrome." (PMID 37661270, 2023). "TNF-α and IL-6 are implicated in dyslipidemia through the secretion of NEFA from visceral fat lipolysis." (PMID 35887592, 2022). "Metabolic syndrome was associated with the elevation of type 1 T helper cells in conjunction with many cytokines, including IL-6 and TNF." (PMID 36431254, 2022). "TNFα is thought to increase insulin resistance and cause dyslipidemia through suppression of adiponectin production." (PMID 35872989, 2022). "Second, increased exercise decreases pro-inflammatory cytokines, including TNF and IL-beta, that are associated with metabolic syndrome." (PMID 36429358, 2022). "Many studies tried to assess the relationship between -308G/A polymorphism of tumor necrosis factor alpha (TNF-α) gene and risk of metabolic syndrome (MS), but their results were contradictory." (PMID 33589701, 2021). "In metabolic syndrome (MS), chronic inflammation is caused by the primary secretion of fat cells of TNFα, and IL6." (PMID 33429991, 2021). "The concentrations of IL-6 and TNF-α are associated with dyslipidemia, a factor that compromises endothelial function." (PMID 34526542, 2021). "High levels of IL-6 and TNF-α in patients with metabolic syndrome are associated with truncal fat mass." (PMID 34326779, 2021). "TNF-α mediated dysregulation in the plasticity of monocytes/macrophages is concomitant with pathogenesis of several inflammatory diseases, including metabolic syndrome, but the underlying mechanisms are incompletely understood." (PMID 33033337, 2020). "One meta-analysis reported that C18:3 administration had great therapeutic potential via decreasing patients’ inflammatory markers (e.g., C-reactive protein, IL-6, and TNF-α) that were associated with metabolic syndrome and related diseases." (PMID 31182969, 2019). "Intermittent Islamic fasting can lower the risk of metabolic syndromes in obese and overweight-weight subjects through reducing weight, BMI, TNF alpha and elevating adiponectin level." (PMID 30881400, 2019). "The increased levels of proinflammatory cytokines (TNF-α, IL-6, and IL-1β) have been found to be important contributors to the underlying processes of the development of metabolic syndrome." (PMID 30863477, 2019). "Inflammatory cytokines, including IL-6 and TNFα, which affect skeletal muscle, the vasculature, and other tissues, cause pathologies associated with frailty and the metabolic syndrome." (PMID 29559978, 2018). "Here, we sought to define the role of metabolic syndrome-associated TNFα production in HFD-induced FGF23 formation." (PMID 29807981, 2018). "The decreases in either IL-6 or TNF-α suggest reductions in subclinical inflammation, which is associated with a lower risk of metabolic syndrome." (PMID 30060746, 2018). "In fact, circulating TNFR levels were associated with dialysis vintage, dyslipidemia, and TNFα (inflammation) in multivariate regression analysis in the present study." (PMID 28256549, 2017). "A meta-analysis of 31 observational studies showed that the TNF-α gene is involved in the pathogenesis of the metabolic syndrome (the 308A variant of this gene has been associated with elevated levels of insulin and blood pressure)." (PMID 27832797, 2016). "VA treatment has been shown to normalize the production of IL-2 and TNFα in mesenteric gut-associated lymph nodes after mitogen stimulation in this rodent model of metabolic syndrome." (PMID 26891736, 2016). "Although blocking TNF activity has been demonstrated to reverse some of the effects of the metabolic syndrome observed in RA, the specific mechanisms in the classifier have not, to our knowledge, previously been associated with response to anti-TNF treatments." (PMID 26036272, 2015).
metabolic syndrome (continued). "We investigated IL-1, IL-6 and TNFα production and toll-like receptor 4 in both—obese and lean patients with non-alcoholic fatty liver disease who met different sets of metabolic syndrome criteria and linked the results with the disease burden." (PMID 26629827, 2015). "Visceral adipose tissue secretes inflammatory cytokines such as interleukin-6 and tumor necrosis factor α, which are associated with both obesity-related glomerulopathy and metabolic syndrome." (PMID 24533159, 2014). "The traditional risk factors for CHD, such as age, dyslipidemia, waist circumference and RI values were associated with IL-1, IL-6 and TNF-α." (PMID 25329057, 2014). "In our laboratory, we tested the possible role of TNF-α in vascular dysfunction associated with the metabolic syndrome by use of the TNF-α neutralizing antibody infliximab." (PMID 24177571, 2013). "Receiver operating characteristic curve analysis revealed that IRAK3 (mean AUC, 95%CI: 0.63, 0.54–0.72, P<0.05), TNFAIP3 (0.65, 0.56–0.73, P<0.01), SOD2 (0.69, 0.60–0.77, P<0.001), and TNFα (0.71, 0.62–0.78, P<0.001) were associated with metabolic syndrome." (PMID 22272346, 2012). "A recent association between apelin and TNF-alpha has been reported in subjects with the metabolic syndrome." (PMID 23227256, 2012). "On the other hand, antiretroviral drugs, especially protease inhibitors as used in the present study, have been associated to a metabolic syndrome associated with an activation of pro-inflammatory cytokines, mainly TNFα." (PMID 21291536, 2011). "The mechanisms underlying the correlation between dyslipidemia and low testosterone levels may involve proinflammatory substances (e.g., TNF-α, IL-8, IL-6, and IL1β)." (PMID 40489567, 2025). "In newly diagnosed patients with metabolic syndrome, TNF-α was significantly associated with fasting blood glucose (r = 0.179, P = 0.021), LDL-C (r = 0.199, P = 0.01), atherogenic index (r = 0.219, P = 0.004), TG (r = 0.351, P < 0.001), and HDL-C (r = -0.244, P = 0.001)." (PMID 40166678, 2025). "Specifically, we focused on TNF-α and IL-6, and a wider range could provide a more comprehensive understanding of the inflammatory mechanisms associated with metabolic syndrome." (PMID 40137151, 2025). "However, this study did not evaluate other major pathological factors associated with lifestyle-related diseases and metabolic syndrome, such as leptin, TNF-α, or interleukin-6." (PMID 40050880, 2025). "At the same time, dyslipidemia is associated with systemic inflammation, characterized by elevated levels of cytokines such as interleukin-6 (IL-6) and tumor necrosis factor-alpha (TNF-α)." (PMID 39891044, 2025). "TNF-α is causally linked to metabolic syndrome through various mechanisms." (PMID 38542788, 2024). "TNF-α is another pro-inflammatory cytokine that has long been linked to dyslipidemia and IR." (PMID 39199499, 2024). "It was, therefore, difficult to decide whether TNF was the cause, risk factor or end-result of other factors, such as metabolic syndrome and elevated cholesterol." (PMID 38396488, 2024). "TNF could, therefore, be considered an independent cardiovascular risk factor in metabolic syndrome." (PMID 38396488, 2024). "Specifically, inflammatory factors, such as TNF-α and IL-6, are associated with dyslipidemia." (PMID 38802874, 2024). "Thus, changes in TNF-α and adiponectin are highly associated with metabolic syndrome and the gut microbiota population." (PMID 36768946, 2023). "Macrophages are already activated in underlying conditions, lifestyle-related diseases, and metabolic syndrome, and they produce large amounts of TNF-α when stimulated by DAMPs (mainly mitochondrial DNA, which damages cells and results in debris) as well as virus particles." (PMID 37569540, 2023). "However, green tea polyphenols increased TTP gene expression but decreased TNF gene expression in rats with metabolic syndrome caused by feeding on a high-fructose diet." (PMID 37189372, 2023).
metabolic syndrome (continued). "Maintaining good gut microbiota suppresses TNF-α, an inflammatory cytokine that is also considered to be a pathogenic contributor adipokine, and prevents chronic inflammation, thereby helping to prevent metabolic syndrome." (PMID 36768946, 2023). "In T2DM, low grade inflammation may also contribute to dyslipidemia as Tumor Necrosis Factor-α (TNF-α) is associated with an increase of intestinal lipoprotein secretion that may elevate chylomicron production in an insulin resistant state." (PMID 36551897, 2022). "Additionally, the reported effects of resveratrol on metabolic syndrome include fat mass reduction, body weight loss, and reductions in the plasma levels of triglyceride, TNF-α and MCP-1." (PMID 34287272, 2021). "Of note, TNF-α may itself promote hyperglycemia and dyslipidemia, thereby further increasing cardiovascular risk." (PMID 34199767, 2021). "Elevated serum TNF-α is associated with dyslipidemia in RA patients." (PMID 35056068, 2021). "It is hypothesized that increasing serum fatty acids associated with metabolic syndrome stimulate TLR4 leading to increased serum levels of TNF-alpha, IL-1B, and IL-6." (PMID 33072103, 2020). "However, increased TNF-α associated with the metabolic syndrome and use of quetiapine has been reported." (PMID 31202268, 2019). "Notably, quercetinsupplementation improves dyslipidemia, hypertensionand hyperinsulinemia as well as weight loss in diabeticmice, by reducing TNF-α production." (PMID 29105398, 2018). "The renal protective effect may be associated with the inhibition of TNF-α/NF-κB-dependent renal inflammation and dyslipidemia, as well as TGF-β1-mediated renal fibrosis." (PMID 28713834, 2017). "Our study indicates that TNF-α signaling is implicated in cardiac insulin sensitivity regulation, further emphasizing promising therapeutic targets for disease conditions with chronic low-grade inflammation, such as metabolic cardiovascular syndrome." (PMID 28304381, 2017). "In NAFLD, oxidative stress may induce production of tumor necrosis factor-α and interleukin-6 and add atherogenic stimuli to the already high oxidative and proinflammatory status that is closely associated with metabolic syndrome." (PMID 26125952, 2015). "This condition is characterized by overproduction of proinflammatory mediators, such as circulating levels of C-reactive protein (CRP), TNF-α, and IL-1β, as well as insulin resistance and dyslipidemia, all of which are risk factors for cardiovascular diseases, metabolic syndrome, and diabetes." (PMID 26490535, 2015). "TNFα has widespread inflammatory effects in the body and has been implicated in harmful changes in adipocytes such as activation of the pro-inflammatory nuclear factor-kappaB (NF-κB) pathway and susceptibility to metabolic syndrome." (PMID 25714093, 2015). "Furthermore, the major risks of ischemic stroke are within the scope of metabolic syndrome, and inflammatory cytokines including hsCRP, TNFα, and IL-6 have been proven to be significantly associated with the occurrence and outcomes of ischemic stroke." (PMID 24716192, 2014). "Inflammation and atherogenic dyslipidemia may be linked by the fact that TNF alpha and IL-6 stimulate lipolysis and increase the flow of free fatty acids to the liver." (PMID 23526980, 2013). "Future studies including this parameter and other relevant biomarkers linked to the metabolic syndrome, e.g. interleukin (IL)-6, tumour necrosis factor (TNF)-α and C-reactive protein (using high-sensitivity assays), should assist in further interpretation of the data obtained." (PMID 19575082, 2009). "However, the acting mechanism underlying TNF‐regulated metabolic syndromes and MASH‐driven HCC progression in humans remains unclear." (PMID 38874196, 2025). "Furthermore, the anti-inflammatory effects of ginger and lemon may contribute by downregulating pro-inflammatory cytokines such as TNF-α, IL-6, and NF-κB—key mediators implicated in both oxidative stress and dyslipidemia." (PMID 40938933, 2025).
metabolic syndrome (continued). "Likewise, in patients with geriatric cachexia, a complex metabolic syndrome characterized by excessive loss of body mass, pro-inflammatory markers such as TNF-α, IL-1, and IL-6 have been linked to symptoms such as decreased gastric motility and emptying, nausea, and vomiting." (PMID 38170327, 2024). "The cytokines and chemokines produced in the lesions reach the blood, so the patient may suffer from comorbidities, especially IL-1β and TNF-α causing cardiovascular complications, metabolic syndromes (such as obesity, dyslipidemia, atherosclerosis, and type 2 diabetes), and autoimmune diseases." (PMID 39513038, 2024). "The metabolic syndrome is associated with the occurrence of chronic inflammation that remains at a low level, which is characterised by the predominance of pro-inflammatory factors in the systemic circulation, e.g., IL-6 and TNFα and IL-18, which are involved in the pathogenesis of LUTS/BPH." (PMID 37847180, 2023). "Hence, the attenuation of TNF-α’s action in the liver may help prevent or delay the development of NASH associated with metabolic syndrome." (PMID 35408923, 2022). "Additionally, higher levels of TNF-α may amplify standard cardiac risk factors such as diabetes and dyslipidemia in patients with RA." (PMID 35056068, 2021). "Attenuation of pro-inflammatory cytokines such as IL-6, TNFα, and IL-1β secreted by immune cells and adipocytes may be a therapeutic approach for treating systemic low-grade chronic inflammation-associated with metabolic syndrome." (PMID 29592806, 2018). "Metabolic syndrome (MetS) is defined as a state of low-grade chronic inflammation, evidenced by elevated serum levels of pro-inflammatory cytokines like tumor necrosis factor alpha (TNF-α) and interleukin-6 (IL-6)." (PMID 41590667, 2026). "Multiple preclinical studies demonstrate that kefir administration reduces pro-inflammatory cytokine levels, including TNF-α, IL-1β, and IL-6, in rodent models of metabolic syndrome." (PMID 40565686, 2025). "Obesity was also linked to elevated levels of TNF-α and PAI-1, whereas insulin resistance, dyslipidemia, and metabolic syndrome were linked to elevated levels of CRP." (PMID 40642705, 2025). "In metabolic syndrome, this is formed through the activation of macrophages and the release of IL-6, TNF-α, and other cytokines." (PMID 41375041, 2025). "Elevated levels of proinflammatory cytokines such as tumor necrosis factor-alpha (TNF-α) and interleukin-6 (IL-6) are common in individuals with metabolic syndrome." (PMID 41393278, 2025). "Further, systemic inflammation, a feature of metabolic syndrome, can inhibit Apo-AI production via inflammatory cytokines such as IL-6 and TNF-alpha." (PMID 41361833, 2025). "They reported significantly lower TNF-α levels and higher IL-10/TNF-α ratios among participants with metabolic syndrome (p = 0.005), suggesting a pro-inflammatory state." (PMID 40722634, 2025). "We therefore evaluated the inflammatory markers IL-6, TNF-α, hsCRP, and metabolic syndrome as potential indicators of ovarian aging and CVD." (PMID 40713717, 2025). "Hepatic steatosis can stimulate Kupffer cells to release inflammatory cytokines such as tumor necrosis factor-alpha (TNF-α) and interleukin-6 (IL-6), thus creating a vicious cycle that exacerbates both IR and dyslipidemia." (PMID 40927334, 2025). "Elevated triglycerides (TGs) align with dyslipidemia in SLE, and a high TG/low HDL profile is linked to systemic inflammation and poor TNFα blockade response." (PMID 40429671, 2025). "A randomized crossover trial in patients with metabolic syndrome demonstrated that the intake of dairy products, including cheese, has significant anti-inflammatory effects, markedly reducing plasma TNF-α levels." (PMID 40717698, 2025). "Probiotics can also benefit the heart by decreasing TMAO, LDL-c, TG, CRP, MDA, TNF-α, IL-6, and urea levels, improving dyslipidemia and toxin profiles." (PMID 40913714, 2025).